SMAD4 (SMAD family member 4)
Diseases named in the same sentence as SMAD4 in open-access papers (continued):
Sharing a sentence is not in itself a finding about the gene and the disease.
cervical carcinoma (25 papers, 2007 to 2024). A carcinoma arising from either the exocervical squamous epithelium or the endocervical glandular epithelium. "In summary, we identified simultaneous mutations in KRAS and SMAD4 in a pre-treatment tumor obtained from a case of stage IB cervical cancer with local recurrence." (PMID 35008475, 2021). "We identified simultaneous mutations in KRAS and SMAD4 in a pre-treatment tumor obtained from a case of stage IB cervical cancer with local recurrence." (PMID 35008475, 2021). "Later, down regulation of SMAD4, which affected the metastatic potentials in early stages of cervical cancer, was associated with TGFB1 down regulation and incriminated cervical cancer." (PMID 26308848, 2015). "Four of 13 cervical cancer cell lines displayed Smad4 deficiency due to insertional inactivation or homozygous loss of 3' exons." (PMID 17997817, 2007). "Through inducible reexpression of Smad4 in cervical cancer cells we wished to shed more light on this issue and to identify target genes implicated in Smad4 dependent tumor suppression." (PMID 17997817, 2007). "The three Smad4 target genes identified in C4-II cervical cancer cells encode secreted proteins which are deposited in extracellular matrices in tissues in vivo." (PMID 17997817, 2007). "Smad4-deficient human C4-II cervical carcinoma cells were used to establish inducible Smad4 reexpression using the commercial Tet-onTM system (Clontech)." (PMID 17997817, 2007). "For example, a loss of Smad4 expression has been reported in cervical cancer tissue." (PMID 24047375, 2013). "We have recently reported loss of Smad4 in every fourth carcinoma of the uterine cervix." (PMID 17997817, 2007). "Thus, we decided to generate stable transfectants from Smad4-deficient C4-II cervical cancer cells conditionally expressing Smad4." (PMID 17997817, 2007). "Loss of Smad4 is a late step in gastrointestinal as well as in cervical cancers, consistent with the hypothesis that Smad4 may function as a suppressor of invasion." (PMID 17997817, 2007). "We further identified that HAT CSRP2BP mediated EMT signalling and cervical cancer metastasis by interacting with SMAD4 to form a complex to activate N-cadherin transcription." (PMID 37845756, 2023). "SMAD4 is a known tumor suppressor in cervical cancer and an essential regulator of the TGF-beta pathway, which has been widely linked to the progression of disease." (PMID 37735483, 2023). "Endogenous CSRP2BP and SMAD4 were expressed in both the nucleus and cytoplasm of cervical cancer cells." (PMID 37845756, 2023). "TGFBR2 has been reported to regulate the Hedgehog pathway and cervical cancer cell proliferation and migration by mediating SMAD4." (PMID 35241117, 2022). "In contrast, despite HPV-positive HNC and cervical carcinomas are both driven by HPV infection, cervical cancer samples showed a high frequency (41%) of LOH at SMAD4 gene locus and similar data were also reported in cervical cancer cell lines." (PMID 35144669, 2022). "Another study demonstrated that downregulation of miR-210 was involved in 1′S-1′-acetoxychavicol acetate (ACA)-induced cervical cancer cell apoptosis by targeting SMAD4." (PMID 34743742, 2021). "Despite an intensive literature search, we were unable to identify uterine cervical cancer cell lines with simultaneous mutations in KRAS and SMAD4, supporting the idea that this mutation signature is rare among uterine cervical cancers." (PMID 30220971, 2018). "In cervical cancer, mutations or loss of TGFβ downstream effectors SMAD2 and SMAD4 are common, and loss of nuclear SMAD2 and SMAD4 is associated with poor survival." (PMID 28219480, 2017). "However, another study demonstrated that overexpression of let-7a interacts with TGF-β1 and SMAD4 and affects cervical cancer cells." (PMID 38632250, 2024).
cervical carcinoma (continued). "Deletion of SBE2 in N-cadherin-Luc (SEBM-Luc) reporter significantly reduced SMAD4/CSRP2BP complex-increased N-cadherin promoter activity, supporting the idea that SMAD4 recruits CSRP2BP specifically to the SBE2 site of the N-cadherin promoter in cervical cancer cells." (PMID 37845756, 2023). "Whether the CSRP2BP/SMAD4 complex coordinates with other factors to control specific H4 acetylation and EMT-associated gene expression in cervical cancer progression and metastasis awaits further investigation." (PMID 37845756, 2023). "SMAD4 is one of the essential transcriptional regulators of EMT-associated genes including N-cadherin and also plays an essential role in the progression of cervical cancer." (PMID 37845756, 2023). "Both weak cytoplasmic Smad4 and the absence of nuclear Smad4 staining were associated with poor survival in cervical cancer patients." (PMID 24047375, 2013). "However this report is in contradiction to another finding that suggested that weak cytoplasmic SMAD4 staining and the absence of Smad4 nuclear staining was associated with poor survival in cervical cancer patients." (PMID 23773282, 2013). "An analysis of 178 cervical carcinomas by The Cancer Genome Atlas (TCGA) network found recurrent deletions of TGF-beta receptor 2 (TGFBR2, 3p24.1) and SMAD4 (18q21.2) in 36% and 28% of analyzed samples, respectively." (PMID 32188026, 2020). "In cervical cancer, it was noticed that the knockdown of either miR-210 or miR-629 sensitizes cells to ACA by upregulating SMAD family member 4 (SMAD4) or Ras suppressor protein 1 (RSU1), respectively." (PMID 33066509, 2020). "The HPV16-positive SiHa human cervical carcinoma cell line is refractory to growth inhibition by TGF-β, which is explained, at least in part, by reduced expression of Smad4 in these cells." (PMID 24047375, 2013). "The same phenomenon of the signaling network contraction in general and specifically a reduction of the TGFβ-Smad4, JAK-STAT and MAPK pathways was observed previously in the in vitro model, based on the initiating event in cervical cancer." (PMID 21410932, 2011). "Given the regulation of N-cadherin expression by CSRP2BP in cervical cancer, we hypothesized that CSRP2BP mediates the N-cadherin expression through SMAD4." (PMID 37845756, 2023). "To probe whether SMAD4 was the key factor by which CSRP2BP activated N-cadherin expression in cervical cancer cells, we used siRNA to knockdown SMAD4 in Hela-CSRP2BP cells and detected changes in SMAD4 and N-cadherin expression." (PMID 37845756, 2023). "Mechanistically, we found that 1) CSRP2BP promoted cervical cancer EMT and metastasis by upregulating N-cadherin, and 2) CSRP2BP increased N-cadherin expression by acetylating H4K5 and H4K12 in the promotor region of N-cadherin through cooperation with Smad4." (PMID 37845756, 2023). "Our results show that Smad4-mediated tumour suppression in cervical cancer cells is not due to restoration of TGF-β growth inhibitory responses." (PMID 17997817, 2007). "We examined several well-known target genes of miR-224, such as Smad4, caspase 3, and TNFAIP1 and found no change in amiodarone-reduced miR-224 cells in a human papillomavirus (HPV)-infected cervical carcinoma cell line, HeLa cells." (PMID 29568365, 2018). "Only few from the cervical carcinoma cell lines display some residual TGF-β responsiveness, irrespective of their Smad4-positive or Smad4-negative status." (PMID 17997817, 2007).
melanoma (25 papers, 2011 to 2025). A malignant, usually aggressive tumor composed of atypical, neoplastic melanocytes. "The investigation revealed that SUZ12, SOX2, TCF3, NANOG and SMAD4 are the maximum chief TFs that control the largest number of genes associated with metastatic-melanoma." (PMID 39820173, 2025). "Under ER stress, SMAD4 expression was significantly up-regulated in melanoma cells with SIRT7 deficiency." (PMID 36918544, 2023). "Further co-IP analysis showed that the interaction between K48-linked ubiquitin chain and SMAD4 was impaired in A2058 melanoma cells with SIRT7 deficiency, whereas significantly increased in WM35 melanoma cells after the overexpression of SIRT7." (PMID 36918544, 2023). "The Smad4 signaling is a promising target for ubiquitination modification in melanoma‐associated T cells." (PMID 28544818, 2017). "In oral cancer, miR-146a targets the HTT gene; in liver cancer, the FLAT mRNA; and in melanoma, SMAD4, regulating cell migration and invasion." (PMID 40277937, 2025). "Five hub genes including CXCL11, ICAM1, LEF1, MITF, and STAT1 were identified, SUZ12, SOX2, TCF3, NANOG, and SMAD4 were determined as the most significant TFs in metastatic-melanoma." (PMID 39820173, 2025). "SIRT7 appears to stimulate the IRE1α-XBP1 pathway in melanoma cells by deacetylating and destabilizing SMAD4." (PMID 38383727, 2024). "Previous studies have demonstrated that specifically knockout of Smad4 in mouse NK cells accelerates the procession of melanoma." (PMID 39439794, 2024). "As the cytoplasmic portion of CD44 interacts with Smad1 in chondrocytes, and promotes phosphorylation of Smad1 and Smad4 and their nuclear translocation, it is likely that a similar mechanism underlies the BMPR co-receptor function for CD44 in melanoma cells." (PMID 30297743, 2018). "Pharmacological inhibition of the TGFBR1 blocked the clonogenicity of human mutant BRAF melanoma cells through SMAD4-independent inhibition of mitosis, and also inhibited metastasis in xenografted zebrafish." (PMID 27835901, 2016). "Instead, we found that Eomes+ CD8+ T cells increased significantly in dLNs of melanoma-bearing mice by the treatment with EW-7197, LY-2157299 or T-cell-specific Smad4 deletion." (PMID 24127404, 2013). "In summary, ALK5 inhibitors have a potent therapeutic efficacy against melanoma by novel mechanisms: inducing the ubiquitin-mediated degradation of Smad4, thereby relieving suppressive effects of TGF-β on Eomes in CTLs." (PMID 24127404, 2013). "TILs increased significantly in the melanomas of Smad4−/− mice, which were rarely observed in those of Smad4+/+ mice." (PMID 24127404, 2013). "EW-7197 and T-cell-specific Smad4 gene targeting enhanced anti-tumour CTL responses with specific upregulation of Eomes in melanoma-bearing mice." (PMID 24127404, 2013). "We observed that TGF-β antagonism by ALK5 inhibition blocked the intact intracellular TGF-β signalling through R-Smads and Smad4 in B16 melanoma cells, and yet they were resistant to TGF-β." (PMID 24127404, 2013). "Accordingly, T-cell-specific deletion of Smad4 was sufficient to suppress the progression of melanoma." (PMID 24127404, 2013). "Significantly more Eomes+ cells infiltrated into the melanomas by EW-7197 or T-cell-specific Smad4 deletion." (PMID 24127404, 2013). "Consistently, EW-7197 exerted the reverse effect of TGF-β on Smad4 subcellular localization: increases in the cytoplasms and decreases in the nuclei of B16 melanoma cells both in vivo and in vitro." (PMID 24127404, 2013). "ALK5 inhibition induced ubiquitin-mediated degradation of Smad4 in CD8+ T cells in addition to the direct inhibition of R-Smad phosphorylation to enhance anti-melanoma CTL responses through derepressing Eomes." (PMID 24127404, 2013). "Furthermore, miR-146a-5p increases cell migration and invasion in melanoma by directly targeting SMAD4." (PMID 38730639, 2024).
melanoma (continued). "Similarly with Smad4 downregulation by EW-7197 treatment, the orthotopic B16 melanoma model using T-cell-specific Smad4 knockout mice showed significant suppression of melanoma growth and LN metastases." (PMID 24127404, 2013). "Notably, ALK5 inhibitors not only blocked R-Smad phosphorylation, but also induced ubiquitin-mediated degradation of the common Smad, Smad4 mainly in CD8+ T cells in melanoma-bearing mice." (PMID 24127404, 2013). "Thus, ALK5 inhibition enhances anti-melanoma CTL responses through ubiquitin-mediated degradation of Smad4 in addition to the direct inhibitory effect on R-Smad phosphorylation." (PMID 24127404, 2013). "To address whether the canonical Smad pathway is involved in the mediation of the TGFβ effects on melanoma self-renewal, we generated specific Smad2, Smad3 and Smad4 knockout (KO) in two different melanoma cell lines, A375m and BLM, using CRISPR genomic editing." (PMID 38201651, 2024). "Moreover, we also examined the interaction between K63-linked ubiquitin chain and SMAD4 after the intervention of SIRT7 in either A2058 or WM35 melanoma cells, and there was no prominent alteration." (PMID 36918544, 2023). "Combining RNAseq with SMAD4 CUT&RUN sequencing, we reveal a novel apoptosis gene signature, which is specific to the double treatment condition and conserved across different melanoma cell lines." (PMID 39709491, 2024). "PLA detected the significantly increased close proximity between ubiquitin and Smad4 in dLN cells, especially in CD8+ T cells of the melanoma-bearing mice treated with EW-7197 or LY-2157299." (PMID 24127404, 2013). "Conversely, the absence of Smad4 in NK cells has been shown to enhance the metastasis of melanoma cells and viral infection." (PMID 39439794, 2024). "Two studies conducted on mouse NK cells have demonstrated that Smad4 play a role in promoting the maturation of mouse NK cells and inhibiting the metastasis of melanoma, regardless of TGF-β signaling." (PMID 39439794, 2024). "Moreover, immunohistochemical analysis in TMA revealed that the staining intensity of SMAD4 was down-regulated in melanoma compared to nevus, and the staining intensities of SIRT7 were negatively correlated with that of SMAD4." (PMID 36918544, 2023). "Collectively, our data proposed the model that SIRT7 deacetylated SMAD4 to trigger its ubiquitination and degradation, thereby relieved the transcriptional suppression on IRE1α to activate IRE1α-XBP1 axis and defend against ER stress in melanoma." (PMID 36918544, 2023). "In both proliferative phenotype melanoma cell lines, knockdown of SMAD4, TAZ, and β-catenin, but not of YAP, significantly counteracted the TGFβ-induced down-regulation of the expression of the melanocyte markers MITF and MLANA." (PMID 34819356, 2022). "Unlike CD8+ T cells, treatment with EW-7197 did not affect the expression levels of total Smad4 protein in both transplanted B16 melanomas in vivo and B16 melanoma cells in vitro." (PMID 24127404, 2013). "Especially, CD8+ cell infiltration was remarkable in the melanomas of Smad4−/− mice, which was absent in those of Smad4+/+ mice." (PMID 24127404, 2013). "Interestingly, we found that blocking Smad3 and Smad4 gene expression but not Smad2 significantly increased melanoma tumorsphere formation in both cell lines." (PMID 38201651, 2024). "Furthermore, TGF-β1 was found to related with regulating clonogenicity of melanoma cells and TGF-β1 inhibition could block the clonogenicity through SMAD4-independent inhibition of mitosis." (PMID 34371697, 2021). "In line with this, CD8+T‐cell infiltration was remarkable in the melanomas of Smad4−/−mice, while it was absent in those of Smad4+/+ mice, suggesting that the inhibition of Smad4 signaling could potentiate antitumor immunity." (PMID 28544818, 2017).
melanoma (continued). "Thus, long-term systemic administration of EW-7197 or T-cell-specific Smad4 deletion did not affect systemic immune homeostasis in C57BL/6 mice without melanoma challenge in a specific pathogen-free (SPF) environment." (PMID 24127404, 2013). "However, pharmacologic ALK5 inhibition in vitro and in vivo did not affect the total expression levels of Smad4 protein in melanoma cells." (PMID 24127404, 2013). "However, downregulation of Smad4 by neither ALK5 inhibition nor T-cell-specific gene targeting affected any CD4+ T-cell subsets in melanoma-bearing mice." (PMID 24127404, 2013). "A total of 4 groups of NSG mice (7 mice/group) received a subcutaneous injection of the non-targeting control, Smad3 and Smad4 CRISPR KOs, generated in the A375m melanoma cell line." (PMID 38201651, 2024). "We showed that although melanoma cells rely on TGFBR1 kinase activity, they do not require SMAD4 for either colony formation, or for the response to TGFBR1 inhibition." (PMID 27835901, 2016).